BRAF (B-Raf proto-oncogene, serine/threonine kinase)
Diseases named in the same sentence as BRAF in open-access papers (continued):
Sharing a sentence is not in itself a finding about the gene and the disease.
melanoma (continued). "In acral location or in sun exposed areas such as the head and neck the odd ratio of carrying a BRAF mutated melanoma declines to 0.25 (acral location) and to 0.61 (head and neck region)." (PMID 27150060, 2016). "Materials and methods: Up to ten melanoma cell lines bearing different mutations in the BRAF gene were exposed to BRAFi and/or MEKi from 2 to 72 h and harvested for protein and RNA extraction." (PMID 27461275, 2016). "A 53-year-old man with metastatic melanoma and dialysis dependent end stage renal failure was treated safely with Vemurafenib for a BRAF V600K mutation positive melanoma and the case was reported elsewhere." (PMID 26989536, 2016). "Since these anti-BRAF targeted therapies are only effective on BRAF V600 mutated melanomas, the detection of BRAF mutations on exon 15, especially on the V600 hotspot is mandatory for prescription." (PMID 27111917, 2016). "For all melanomas analyzed (from all localities in NZ), BRAF mutations were identified in 33.1% of melanomas (175/529), and were detected by either MelaCarta and/or Sanger sequencing." (PMID 27191502, 2016). "In fact, the overexpression of the wild type BRAF vs the mutated BRAFV600E in melanoma cells leads to increased basal levels of autophagy." (PMID 26735341, 2016). "BRAF, for example, is known for its activating mutation V600E, an important actor for the proliferation of melanoma cells." (PMID 27998306, 2016). "A total of 529 melanomas were analyzed for BRAF exon 15 mutations by Sanger sequencing, and also by Sequenom MelaCarta MassARRAY." (PMID 27191502, 2016). "In papillary thyroid carcinoma and melanoma BRAF oncogenic mutations were highly prevalent and led to deregulation of several miRNAs involved in tumor formation." (PMID 26646588, 2016). "Some studies have reported that the activation of the mitogen-activated protein kinase (MAPK) signaling pathway, as a result of the somatic mutation of BRAF, is a crucial event in the development of melanoma." (PMID 27313934, 2016). "The identification of BRAF mutations offered an opportunity to test novel oncogene-targeted therapies for melanoma." (PMID 27563819, 2016). "Recently, genetic subsets of melanoma have been characterized, especially with known driver mutations such as BRAF, NRAS, GNAQ, RAC1, C-KIT, and others." (PMID 26871475, 2016). "Materials and methods: Energetic metabolism of melanoma cell lines with different BRAF mutational status was studied through the evaluation of oxygen consuption, ATP, lactate and ROS levels." (PMID 27461275, 2016). "The majority of human melanomas express mutations in BRAF, and because of this mutation, much effort has gone into targeting BRAF and downstream pathways." (PMID 26871475, 2016). "As such, trametinib has been shown to be a potent inhibitor of cancer cell proliferation and has been approved by the FDA for the treatment of melanoma with BRAF mutations." (PMID 27911862, 2016). "Similar to previous studies, mutations in the BRAF oncogene were the most frequent in our cohort of NZ melanomas." (PMID 27191502, 2016). "Studies have shown that BRAF signaling also induces Brn-2 expression, which revealed that Brn2 is a focus for the convergence of two key melanoma associated signaling pathways that are linked to cell proliferation." (PMID 27148169, 2016). "Recent advances in the understanding of melanoma biology have resulted in some targeted therapies such as BRAF inhibitors for metastatic melanomas with BRAF-mutations." (PMID 27472394, 2016). "Results of the Boyden chamber invasion assay clearly demonstrated that fisetin potentiated the anti-invasive potential of sorafenib in BRAF-mutated melanoma cells." (PMID 26517521, 2016). "It is now well documented that long-term exposure of melanomas to BRAF inhibitors is associated with a rapid development of drug resistance, and this is mainly linked to the rewiring of the MAPK/ERK signaling pathway." (PMID 27833586, 2016).
melanoma (continued). "Fifty percent of patients displaying mutated BRAF melanomas also develop intrinsic/innate resistance at an early stage during treatment." (PMID 27596438, 2016). "Although current understanding of HCL genetics is incomplete, the BRAF V600E mutation is found in the vast majority of HCL cases, compared with the 40–60 % of melanomas that contain a range of BRAF mutations." (PMID 26857260, 2016). "Her melanoma was confirmed as containing the BRAF V600E mutation, and she was commenced on vemurafenib at the standard starting dose of 960 mg twice daily (BD) in January 2012, as part of an expanded access programme." (PMID 26857260, 2016). "It has been reported that melanoma treated with an oncogenic (V600E) BRAF inhibitor can become resistant by acquiring mutations in an upstream activator, N-RAS." (PMID 27608848, 2016). "In melanoma the TERT promoter mutations occur together with BRAF and NRAS mutations more frequently than per chance, suggesting a link between TERT expression and MAPK pathway activation during immortalization of melanocytes via ETS proteins." (PMID 27449293, 2016). "Recognized for their BRAFV600E mutation and sensitivity to BRAF inhibition, melanoma cells were included in our drug screens as a reference." (PMID 26942566, 2016). "In detail, the likelihood to carry a BRAF mutation is highest if the primary melanoma is located on the trunk." (PMID 27150060, 2016). "This has specifically been described in PTC as well as melanomas where BRAF mutations were present in normal skin distant from nevi." (PMID 27656301, 2016). "The reason for this is its central role in melanoma, which is reflected in its frequent deregulation through mutations, and these are found even more frequently in BRAF/MEK inhibitor resistant tumors." (PMID 27200346, 2016). "Activating mutations in BRAF are found in almost half of all melanomas, and of these mutations, almost 90% involve a valine to glutamic acid transition at position 600 (BRAFV600E)." (PMID 26885666, 2016). "RMEL3 expression was also significantly increased in melanomas with a BRAFV600E mutation compared to those with a wild type BRAF or triple wild type for BRAF/RAS/NF1, an association also observed in a panel of human melanoma cell lines." (PMID 27167340, 2016). "To investigate if inhibition of hsa-miR-210 would impact the cells response to targeted therapies, we treated mice with MEK inhibitor trametinib, since this is an approved treatment against BRAF mutated melanoma." (PMID 27009863, 2016). "In 22 (40%) patients melanomas were BRAF wild-type, 23 (42%) showed a BRAF mutation, and 10 (18%) a NRAS mutation." (PMID 27213536, 2016). "Accordingly, BRAF inhibitors targeting the V600 mutations were developed to preserve EGFR responses in melanoma, and they are anticipated to be effective in various cancers associated with BRAF V600 mutations." (PMID 27094161, 2016). "Recent data show that mutations in genes responsible for common nevi or melanomas such as BRAF, NRAS, or c-kit are actually rare in blue nevi." (PMID 27313934, 2016). "These two melanoma cell types, both carrying the point mutation of V600 (exon 15) in BRAF gene and wild type sequence of hot-spot regions exon 1 and 2 in NRAS gene, were then seeded and cultivated separately." (PMID 27175588, 2016). "The discovery of the oncogenic V600E driver mutation in BRAF, which is present in ~50% of melanomas, led to the development of vemurafenib and dabrafenib, which are inhibitors of the mutant BRAF kinase." (PMID 27959922, 2016). "BRAF is commonly mutated in melanomas on intermittently sun-exposed skin while those on mucosal membranes, acral skin (soles, palms, and nail bed), and skin with chronic sun-induced damage only rarely show mutations." (PMID 28101108, 2016). "BRAF V600E is an actionable mutation in melanoma with significantly prolonged survival when a BRAF inhibitor is administered in patients with this mutation, but it is not actionable in colorectal adenocarcinoma." (PMID 26684240, 2016).
melanoma (continued). "In patients with advanced melanoma the detection of BRAF mutations is considered mandatory before the initiation of an expensive treatment with BRAF/MEK inhibitors." (PMID 27150060, 2016). "We found that combination treatment (fisetin + sorafenib) more effectively reduced the migration and invasion of BRAF-mutated melanoma cells both in vitro and in raft cultures compared to individual agents." (PMID 26517521, 2016). "The presence of the BRAF V600E activating mutation, found in approximately half of the diagnosed melanomas, is a turning point in the treatment of the metastatic disease through BRAF-TIKs." (PMID 26968814, 2016). "Approximately 40–60% of melanomas carry a BRAF mutation, which is known to enhance cell proliferation by activation of downstream signalling through MAPK pathway." (PMID 26989536, 2016). "Surprisingly, we also found that NRAS-mutant melanoma cells were significantly more resistant to the drugs that induce DNA replication stress than were BRAF-mutant, NF1-deficient, or triple wild-type melanomas." (PMID 27608486, 2016). "We found that fisetin also inhibited expression of Snail1 in BRAF-mutated melanoma cells in vitro as well as in xenograft tumors." (PMID 26517521, 2016). "Selective inhibition of BRAF by vemurafenib results in objective clinical responses in around 50 % of patients suffering from BRAFV600 mutated melanoma." (PMID 27075584, 2016). "BRAF inhibitors such as vemurafenib and dabrafenib shows promising effect in BRAF mutated advanced melanoma patients." (PMID 27399673, 2016). "The MART-1+ xMD-selected melanoma cells demonstrated a substantial increase in BRAF and MET mutation frequency compared to the macrodissction of the admixture." (PMID 26999048, 2016). "Overall, BRAF mutations were observed in approximately one third of melanomas in NZ (175/529; 33.1%)." (PMID 27191502, 2016). "Overexpression of the BRAF V600E oncoprotein caused resistance but also dependency on BRAF inhibitor therapy in melanoma xenografts." (PMID 26949746, 2016). "Oncogenic mutations of BRAF have been implicated in changes of the metabolic phenotypes seen in melanoma favoring a shift towards more oxidative and less glycolytic metabolism." (PMID 27285585, 2016). "A previous study indicated that HGF facilitates resistance to BRAF inhibitor in malignant melanoma cells with an oncogenic BRAF mutation." (PMID 27683122, 2016). "The v-raf murine sarcoma viral oncogene homolog B1 (BRAF) gene is mutated in 40–60 % of melanomas, the most common being the V600E mutation, which leads to over-activation of the mitogen-activated protein kinase (MAPK) pathway." (PMID 26857260, 2016). "Since the first description of BRAF mutations in melanoma BRAFV600E, the most predominant mutant, has been shown to constitutively activate ERK in melanocytes, and to transform p16/INK4A deficient melanocytes." (PMID 27200346, 2016). "The majority of melanomas harbor BRAF (V600E) mutations leading to the constitutive activation of the MAPK signaling pathway." (PMID 27834845, 2016). "We determined the effects of fisetin (which targets PI3K signaling), sorafenib (an RAF inhibitor) and their combination on EMT marker proteins in BRAF-mutated melanoma cells." (PMID 26517521, 2016). "Our study supports that RASA1 suppresses melanoma growth at least in part by regulating R-Ras activity in melanoma cells harboring oncogenic BRAF mutations." (PMID 26993606, 2016). "The frequency of BRAF mutations varies widely in human cancers, from more than 80% in melanomas and nevi, to as little as 0-18% in other tumors, such as 1-3% in lung cancers and 5% in colorectal cancer." (PMID 26767073, 2016). "BRAF mutations are present in about 50% of melanomas, causing an over-activation of the MAPK/ERK pathway involved in cell proliferation and survival." (PMID 26863566, 2016).
melanoma (continued). "Specific examples include the use of EGFR tyrosine kinase inhibitors in non-small cell lung cancer (NSCLC) with an EGFR mutation, BRAF inhibitors in melanoma harboring BRAF mutations, or imatinib for chronic myelogenous leukemia." (PMID 26848768, 2016). "To determine the frequency of double mutations in early passage cultures in general in a larger patient cohort, we Sanger sequenced the NRAS locus in all BRAF-mutated cell cultures generated from 2013—2015 archived in our melanoma biobank." (PMID 27791198, 2016). "In this study we applied four BRAF-mutated melanoma cell lines derived from lymph node or brain metastases and stably labeled with GFP-luciferase (further referred as Luc+)." (PMID 26918352, 2016). "Vemurafenib proved effective in melanoma patients harboring BRAF mutations with a response rate of greater than 50% and a rapid improvement in quality of life." (PMID 27096871, 2016). "Almost 50% of melanomas harbor activating mutations in the BRAF oncogene, predominantly V600E, leading to constitutive activation of the mitogen activated protein kinase (MAPK) pathway." (PMID 27655717, 2016). "The selected cell line's mutations represented melanoma - eight CDX samples originated from BRAF mutant melanoma, SK-MEL-2 harbored an activating Q61R NRAS mutation and MeWo carried multiple NF1 inactivating mutations." (PMID 27009863, 2016). "Activating mutations in BRAF, present and in up to 70% of all melanomas along with NRas mutations (present in approximately 15–20% of melanomas), result in constitutive activation of MAPK signaling, promoting growth, survival, and chemoresistance." (PMID 27882308, 2016). "After the discovery of BRAF mutations, clinical trials of targeted therapies of advanced melanoma show significant improvement." (PMID 27042173, 2016). "Except for acral and mucosal melanomas, BRAF mutations are an early genetic event of melanoma tumourigenesis and can be found in up to 60 % of frank melanomas." (PMID 26850723, 2016). "Allele-specific quantitative PCR analysis for BRAF V600 E/E2/D/K/R/M mutations was performed on DNA extracted from plasma of patients with known BRAF V600 mutant melanoma who were treated with dabrafenib and trametinib." (PMID 27095081, 2016). "Melanoma progression can depend on BRAF mutations, which are able to induce and maintain the activation of the MAPK pathway in the absence of growth factor signals." (PMID 26981153, 2016). "In this study, BRAF V600mut ctDNA was detected at baseline in 75 % of stage IV melanoma patients with a known BRAF V600 mutation." (PMID 27095081, 2016). "BRAF kinase inhibitors: Vemurafenib and dabrafenib are approved for treatment of late-stage melanoma with BRAF mutation." (PMID 25902737, 2016). "1205LU melanoma cells carry the BRAF V600E activating mutation responsible to maintain an activated MAPK/ERK pathway, reflected in high levels of pERK1/2." (PMID 27102439, 2016). "Many clinical melanoma patients have BRAF V600 mutation, such as V600E or V600D which confers melanoma cells the capacity of metastasis." (PMID 26747087, 2016). "Melanomas frequently harbor mutations in oncogenes like BRAF, NRAS (neuroblastoma RAS viral oncogene homolog), KIT (v-kit Hardy–Zuckerman 4 feline sarcoma viral oncogene homolog) and tumor suppressors CDKN2A and PTEN." (PMID 26846696, 2016). "The results reported here should encourage the inclusion of patients with BRAFV600R-mutated malignant melanomas in future prospective clinical trials with BRAF inhibitors." (PMID 27255157, 2016). "In the melanoma patient cell-free DNA, the BRAF V600E allele frequency was increased at shorter fragment lengths compared to the WT allele." (PMID 27428049, 2016). "Since mutational activation of BRAF is frequently observed in melanoma, we tested the susceptibility of immortalised mouse melanocytes stably transfected with either wild-type or mutant BRAF to inhibition by the TGFBR1 kinase inhibitor SB-431542." (PMID 27835901, 2016).
melanoma (continued). "More importantly, the in vitro anti-invasive effects of fisetin and sorafenib against BRAF-mutated melanoma were translated under in vivo conditions." (PMID 26517521, 2016). "BRAFV600K mutations were detected in 4.3-4.5% of melanoma samples (MelaCarta, 21/466; or MelaCarta plus Sanger, 23/529) and these comprised 13.2%-15.0% of BRAF mutations detected." (PMID 27191502, 2016). "BRAF inhibitors, vemurafenib and dabrafenib, have been approved for use in melanoma patients who are BRAF V600E/V600K mutation carriers, these agents have been shown to significantly improve survival in BRAF-mutated melanoma patients." (PMID 27582542, 2016). "BRAF mutations have also been associated with malignancies, such as melanoma, thyroid carcinoma, and colorectal carcinoma." (PMID 27255157, 2016). "Materials and methods: From November 2013 to September 2015, we have collected data from 54 patients with BRAF V600E/K mutation-positive stage IV melanoma." (PMID 27461275, 2016). "The use of BRAFi significantly increases the response rate, and prolonged progression-free and overall survival in melanoma patients with BRAF mutation." (PMID 27042173, 2016). "On the other hand, in melanoma cells harboring BRAF mutations, only the MEK/ERK signaling cascade was shown to be overactivated." (PMID 27833586, 2016). "About 50 per cent of melanomas show a mutation in the BRAF gene, with valine substituted for glutamate at codon 600, and this mutation is known as V600E or V600K." (PMID 27841141, 2016). "Fisetin and sorafenib reduced the expression of Snail1, Twist1, Slug and ZEB1 in BRAF-mutated melanoma cells." (PMID 26517521, 2016). "BRAF V600E mutations have been reported as oncogenic mutation or resistant mutation to drugs in melanoma and thyroid cancer, GIST, hairy cell leukemia, multiple myeloma, and pediatric metanephric tumors." (PMID 26684240, 2016). "When trametinib was compared with chemotherapy (DTIC or paclitaxel) in 322 patients with BRAF-mutated melanoma, median PFS and 6 month OS rates were greater in the trametinib group, at 4.8 months and 81%, versus 1.5 months and 67% in the chemotherapy group." (PMID 26784231, 2016). "Approximately 50% of melanomas harbor a mutation in the BRAF gene, which leads to the dysregulated downstream activation of the MEK/ERK signaling pathway." (PMID 27583134, 2016). "Our observation is consistent with a recent report that loss of a RasGAP, Nf1, cooperates with BRAF activation in melanoma tumorigenesis in a genetically engineered mouse model." (PMID 26993606, 2016). "In recent years, several drugs have been approved for the treatment of patients with advanced stage melanoma harboring BRAF mutations." (PMID 27447748, 2016). "The aims of this study were to investigate the efficacy of hvTRA alone and in combination with the mutated BRAF inhibitor vemurafenib in melanoma cell lines, xenograft model and patient materials." (PMID 28028438, 2016). "Among the BRAF mutations detected in melanoma, over 80% are represented by a single nucleotide mutation characterized by a glutamic acid for valine at codon 600 (BRAFV600E)." (PMID 27563819, 2016). "High and low NRAS and BRAF mutation frequencies, respectively, have implications for the diagnosis, and treatment of melanoma in NZ." (PMID 27191502, 2016). "In the present study, we showed that ETS1 is expressed in melanoma cell lines and is constitutively phosphorylated by ERK on Thr38 in melanoma cell lines due to the activation of the MAPK pathway associated with BRAF or NRAS mutations." (PMID 27449293, 2016). "Again, in humans, it is epidermal melanocytes that develop into melanoma in response to NRAS or BRAF mutations." (PMID 27166257, 2016). "Our results, supported by the evidence of the literature, suggest the use of an algorithm in the melanoma BRAF diagnostic setting." (PMID 27863476, 2016).